PTCHD3 (patched domain containing 3 (gene/pseudogene))
Description:
May play a role in sperm development or sperm function. However, does not appear to have an essential role in spermatogenesis or male fertility.
Synonyms: PTR; SLC65C3; FLJ44037
Gene: Protein-coding gene on chromosome 10 (27,397,121 to 27,414,368, reverse strand). Ensembl gene ENSG00000182077.
Subcellular location: Cell projection, cilium, flagellum membrane; Endoplasmic reticulum membrane
Genetic constraint (gnomAD): Missense variants: 1,005 observed, 925.03 expected, observed/expected ratio (o/e) 1.09, 90% interval 1.03 to 1.14. Synonymous variants: 412 observed, 378.01 expected, observed/expected ratio (o/e) 1.09, 90% interval 1 to 1.18.
Homologues: Orthologues: macaque PTCHD3 (92% identical), chimpanzee PTCHD3 (79% identical), rat Ptchd3 (68% identical), mouse Ptchd3 (67% identical), pig PTCHD3 (64% identical), guinea pig PTCHD3 (58% identical), zebrafish ptchd3l (40% identical), tropical clawed frog PTCHD3 (38% identical), zebrafish ptchd3a (29% identical), Drosophila melanogaster Ptr (28% identical), dog PTCHD3 (25% identical), Caenorhabditis elegans ptr-17 (22% identical), and 4 more. Paralogues in human: PTCHD1 (22% identical), NPC1L1 (22% identical), NPC1 (21% identical), PTCHD4 (20% identical), PTCH1 (19% identical), PTCH2 (19% identical), DISP1 (15% identical), DISP3 (15% identical), DISP2 (13% identical), SCAP (9% identical).
Diseases named in the same sentence as PTCHD3 in open-access papers:
PTCHD3 is named in the same sentence as 9 diseases in open-access papers, as found by Europe PMC text mining. Sharing a sentence is not in itself a finding about the gene and the disease. The quoted sentences say what the papers report.
asthma (2 papers, 2017 to 2020). "SNPs in PTCHD3 gene were previously associated with asthma in African American children." (PMID 33303027, 2020).
autism spectrum disorder (1 paper, 2011). A spectrum of developmental disorders that includes autism, and Asperger syndrome. "In a genomic screen investigating CNV in Autism Spectrum Disorders (ASDs) we detected a heterozygous deletion on chromosome 10p12.1, spanning the Patched-domain containing 3 (PTCHD3) gene, at a frequency of ~1.4% (6/427)." (PMID 21439084, 2011).
colorectal cancer (1 paper, 2019). A primary or metastatic malignant neoplasm that affects the colon or rectum. "For PTCHD3, it is a gene generally expressed in germ cells of the testis, and what the most interesting observation is that there are only two reports about its possible correlation with colorectal cancer." (PMID 30704464, 2019).
inflammatory bowel disease (1 paper, 2022). A spectrum of small and large bowel inflammatory diseases of unknown etiology. "In addition, 4 of the signals detected when CRC was compared with inflammatory bowel disease patients were suggestive: in the HLA region, in the DLGAP2 gene, downstream of the PTCHD3 gene and upstream of the ATP8B4 gene." (PMID 36077729, 2022).
cancer (2 papers, 2019 to 2024). A tumor composed of atypical neoplastic, often pleomorphic cells that invade other tissues. "CDKN2A has been widely reported to act as a potential biomarker, while there were few reports about the cancer risk of abnormal expression of PTCHD3, which definitely shed light on the intensive investigation of PTCHD3 for its role in cancers." (PMID 30704464, 2019). "PTCHD3 gene was selected as a discriminating gene in 3 out of the 6 cancers, which suggested that it might play important role in the cancer risk and would be worthy for the intensive investigation." (PMID 30704464, 2019). "And the PTCHD3 gene, which indicated discriminating ability in cancer prediction in three cancers, was worth for further exploring." (PMID 30704464, 2019). "The discriminating genes that most commonly shared among the 6 cancers were CDKN2A and PTCHD3, which were both selected in three cancers." (PMID 30704464, 2019). "As PTCHD3 indicated its discriminating ability in three cancers in our research, we speculate that it may be a potential biomarker for PRAD, HNSC and KIRP, and it is meaningful to carry out biological validation in the next step." (PMID 30704464, 2019).
PTCHD3 also shares sentences with these, for which no sentence is quoted: tumor (3 papers); autism (2); myocarditis (1); prostate carcinoma (1).